ENSG00000288534 (TMX2-CTNND1 readthrough (NMD candidate))
Synonyms: CTNND1; p120(ctn); TMX2-CTNND1
Gene: Protein-coding gene on chromosome 11 (57,712,582 to 57,818,431, forward strand). Ensembl gene ENSG00000288534.
Genetic constraint (gnomAD): Missense variants: 145 observed, 136.4 expected, observed/expected ratio (o/e) 1.06, 90% interval 0.93 to 1.22. Synonymous variants: 65 observed, 57.78 expected, observed/expected ratio (o/e) 1.12, 90% interval 0.92 to 1.38.